RNF208 (ring finger protein 208)
Synonyms: DKFZP761H1710
Tractability: No criterion of Open Targets' tractability assessment is met for any kind of drug.
Gene: Protein-coding gene on chromosome 9 (137,220,246 to 137,222,290, reverse strand). Ensembl gene ENSG00000212864.
Subcellular location (Human Protein Atlas): Nucleoplasm
Gene Ontology:
Molecular function: protein binding; ubiquitin-protein transferase activity; ubiquitin protein ligase activity
Biological process: protein autoubiquitination; protein ubiquitination
Cellular component: nucleoplasm
Genetic constraint (gnomAD): Loss-of-function variants: 7 observed, 12.26 expected, observed/expected ratio (o/e) 0.57, 90% interval 0.32 to 1.07. The synonymous counts are far from expectation, so gnomAD's model fits this gene poorly and the ratio says little. Missense variants: 342 observed, 340.33 expected, observed/expected ratio (o/e) 1, 90% interval 0.92 to 1.1. Synonymous variants: 211 observed, 156.02 expected, observed/expected ratio (o/e) 1.35, 90% interval 1.21 to 1.52.
Homologues: Orthologues: chimpanzee RNF208 (100% identical), macaque RNF208 (99% identical), mouse Rnf208 (94% identical), rat Rnf208 (94% identical), pig RNF208 (93% identical), dog RNF208 (93% identical), guinea pig RNF208 (89% identical), tropical clawed frog rnf208 (66% identical), zebrafish RNF208 (52% identical). Paralogues in human: RNF223 (16% identical), RNF225 (16% identical), RNF183 (13% identical).
Diseases named in the same sentence as RNF208 in open-access papers:
RNF208 is named in the same sentence as 6 diseases in open-access papers, as found by Europe PMC text mining. Sharing a sentence is not in itself a finding about the gene and the disease. The quoted sentences say what the papers report.
triple-negative breast carcinoma (4 papers, 2019 to 2024). An invasive breast carcinoma which is negative for expression of estrogen receptor (ER), progesterone receptor (PR), and human epidermal growth factor receptor 2 (HER2). "RNF208 decreases the stability of soluble Vimentin protein through a polyubiquitin-mediated proteasomal degradation pathway, thereby suppressing metastasis of triple-negative breast cancer (TNBC) cells." (PMID 33194647, 2020). "The exact role of RNF208 in CRC is not yet fully understood, but evidence suggests that its overexpression can inhibit tumor formation and lung metastasis of triple-negative breast cancer cells." (PMID 38576045, 2024). "Specifically, in triple-negative breast cancer (TNBC), RING finger protein 208 (RNF208), an estrogen-inducible E3 ligase, targeted soluble vimentin for polyubiquitin-mediated proteasomal degradation, thereby suppressing metastasis." (PMID 36631457, 2023).
breast carcinoma (2 papers, 2019 to 2024). "Taken together, these results suggest that RNF208 expression is closely associated with Vimentin-mediated aggressive cancer progression of breast cancer cells." (PMID 31862882, 2019). "To assess the molecular mechanism underlying RNF208 function in breast cancer progression, we performed a mass spectrometry-based formaldehyde crosslinking assay in RNF208-overexpressing MDA-MB-231 cells." (PMID 31862882, 2019). "Taken together, these results suggest that RNF208 is closely associated with aggressive breast cancer and may serve as a predictive factor for the risk of developing relapse disease in breast cancer patients." (PMID 31862882, 2019). "We then investigated whether the loss of RNF208 increases the aggressive potential in the luminal subtype of breast cancer cells." (PMID 31862882, 2019). "Because RNF208 expression was increased in luminal breast cancer subtypes, which are ERα-positive, we investigated the relationship between RNF208 and ERα expression using public microarray datasets (GSE2034; GSE5460)." (PMID 31862882, 2019). "We further analyzed RNF208 expression in different breast cancer subtypes using microarray and RNA sequencing datasets of breast cancer patients obtained from Genomic Data Commons (GDC) datasets and public microarray datasets." (PMID 31862882, 2019). "We next prompted an investigation of the relevance between RNF208 and Vimentin expression in patients with breast cancer." (PMID 31862882, 2019). "Further studies will be required for deeper insight into the role of RNF208 in ERα/β-dependent or -independent pathways during breast cancer progression." (PMID 31862882, 2019). "Based on the transcriptome analysis, we found that RNF208 was significantly underexpressed in TNBC cells compared to luminal breast cancer cells (GSE100878)." (PMID 31862882, 2019). "Indeed, a significant inverse relationship between RNF208 and Vimentin expression was observed in matched tumor tissues of patients with breast cancer." (PMID 31862882, 2019). "Our findings led us to verify the physiological function of RNF208 in breast cancer progression." (PMID 31862882, 2019). "In addition to the overexpression of RNF208 in luminal subtype breast cancers, our results indicated that RNF208 serves as an estrogen-inducible protein that plays a role in blocking the aggressiveness of breast cancers." (PMID 31862882, 2019). "The expression of RNF208 was positively correlated with the ERα status in breast cancers." (PMID 31862882, 2019). "Moreover, gene expression analysis of a public microarray dataset (GSE41313) with 52 breast cancer cell lines showed significantly lower expression of RNF208 in TNBC cells compared to luminal cells." (PMID 31862882, 2019). "Furthermore, public microarray datasets revealed a significant correlation of RNF208 expression with expression status of ERα in human breast cancers." (PMID 31862882, 2019). "Thus, our findings strongly suggest that RNF208 expression may be a significant prognostic marker to predict breast cancer progression, depending on ERα expression status." (PMID 31862882, 2019). "In breast cancer cells, RING finger protein 208 (RNF208) is found to play an inhibitory role in metastasis by interacting with phosphorylated Vimentin Ser39 residues." (PMID 38191501, 2024). "In addition, given that the ERα expression status is strongly linked to breast cancer subtypes, RNF208 may be useful as a prognostic marker in breast cancers, and modulation of RNF208 in an ERα-dependent manner may be a therapeutic intervention against metastatic breast cancers." (PMID 31862882, 2019). "Therefore, RNF208 plays a negative role in aggressive breast cancer progression by destabilizing AKT-mediated phosphorylation of soluble Vimentin." (PMID 31862882, 2019). "Moreover, the low expression of RNF208 was strongly correlated with poor relapse-free survival, regardless of breast cancer subtypes." (PMID 31862882, 2019).
breast carcinoma (continued). "Therefore, we expect that the induction of RNF208 via ERα re-expression by using epigenetic agents may exert anticancer effects in ERα-negative breast cancers." (PMID 31862882, 2019). "However, because the molecular classification of breast cancer subtypes is mainly defined by ERα expression and most of public gene expression profiles do not fully reflect different profiles between ERα and ERβ, we could not analyze the correlation between RNF208 and ERβ expression." (PMID 31862882, 2019).
breast tumor (1 paper, 2019). "We next examined the RNF208 protein and mRNA levels in human primary breast tumor specimens by immunohistochemistry staining and quantitative RT-PCR." (PMID 31862882, 2019).
metastatic cancer (1 paper, 2019). A carcinoma which has spread from the original site of growth to another anatomic site. "Because Vimentin is associated with the mesenchymal phenotype of aggressive cancer cells in metastatic cancer progression, we first investigated whether RNF208 regulates the expression of EMT markers in Hs578T and MDA-MB-231 cells." (PMID 31862882, 2019).
tumor (5 papers, 2019 to 2024). "Lastly, RNF208 is directly implicated in Vimentin degradation and has been linked to the aggressiveness of various tumor cell lines, with its loss enhancing dissemination and metastasis spreading." (PMID 39199549, 2024). "Because tumorigenic potential is closely associated with enhanced invasiveness for metastasis of tumor cells, we next examined whether RNF208 affects cell migration and invasiveness using Transwell migration and Matrigel invasion assays." (PMID 31862882, 2019). "Overexpression of RNF208 dramatically attenuated the tumor volume of TNBC cells." (PMID 31862882, 2019). "Overexpression of RNF208 suppresses tumor formation and lung metastasis of TNBC cells." (PMID 31862882, 2019). "Furthermore, expression of Vimentin was decreased in RNF208-ovexexpressing primary tumor tissues compared with control tissues in xenograft mouse experiment." (PMID 31862882, 2019). "Furthermore, expression of Ki-67, a marker of cell proliferation, was decreased, whereas active caspase-3, a marker of cell death, was increased in RNF208-overexpressing primary tumor tissues compared with control tissues." (PMID 31862882, 2019). "Notably, the expression of RNF208 was remarkably lower in the tumor compartments of patients with TNBC compared to those with the luminal subtypes, and RNF208 mRNA was significantly decreased in TNBC tissues." (PMID 31862882, 2019). "Taken together, these results strongly suggest that RNF208 may act as a tumor suppressor in the cancer progression of TNBC cells." (PMID 31862882, 2019). "Considering that the lack of RNF208 in patients with TNBC seems to be due to exclusive downregulation of ERα, it is feasible that upregulation of RNF208 induced by re-expression of ERα in TNBC cells may act as a tumor suppressor." (PMID 31862882, 2019).
cancer (2 papers, 2019 to 2021). A tumor composed of atypical neoplastic, often pleomorphic cells that invade other tissues. "Further studies will be required to better understand the PTMs of RNF208 in various cancer cells." (PMID 31862882, 2019). "Notably, RNF208 and Vimentin were inversely expressed in patients with luminal subtype cancer and TNBC tissues." (PMID 31862882, 2019).